BTK (Bruton tyrosine kinase)
Diseases named in the same sentence as BTK in open-access papers (continued):
Sharing a sentence is not in itself a finding about the gene and the disease.
lymphoma (continued). "In summary, these findings indicated that JDB175 is a novel and highly selective BTK inhibitor that exhibited potent suppression of lymphoma cells." (PMID 37929016, 2023). "The seroconversion rate increased after the second dose, although it was still lower in HM patients (65.3% vs. 97.8%) mainly due to low seroconversion rate in patients with CLL and B-cell leukemia/lymphoma treated with anti-CD20 antibodies or BTK inhibitors." (PMID 37106746, 2023). "An example of such an approach is the recently published PBPK model for vincristine and its application to predict potential drug–drug interactions with Bruton tyrosine kinase inhibitors being added to R‐CHOP protocols for lymphoma." (PMID 36631976, 2023). "JDB175 effectively inhibits the BTK signaling pathway in human lymphoma cells, suppressing their proliferation, inducing cell cycle arrest, and promoting apoptosis." (PMID 37929016, 2023). "The BCR signalling pathway plays an important role in the development of lymphoma, and BTK is a key protein that mediates signalling to the downstream pathways, including the NF-κB pathway." (PMID 36830087, 2023). "Bruton’s tyrosine kinase (BTK) is highly expressed in various of lymphoma cells and plays an essential role in B-cell receptor (BCR) signal and B cell activation." (PMID 36733714, 2023). "Of note, the pattern of LCK expression is similar to oncogenes SYK and BTK, which are known drivers of B-cell leukemia and lymphoma." (PMID 36711753, 2023). "In patients with lymphoma, B-cell-depleting therapies such as anti-CD20 monoclonal antibodies, BTK inhibitors and CAR-T were associated with unfavorable outcomes of COVID-19." (PMID 37106746, 2023). "This case report describes the duration and genetic study of a patient with malignant lymphoma who was infected with SARS-CoV-2 during BTK inhibitor therapy and who sustained persistent infection for over 6 months." (PMID 36676732, 2023). "An important point is that BTK inhibitors can cross the blood–brain barrier and have demonstrated activity in primary central nervous system (CNS) lymphoma." (PMID 38068428, 2023). "As a result, there is currently a considerable interest in developing BTK inhibitors to treat lymphoma." (PMID 37929016, 2023). "Preclinical data suggest that the IRAK4 inhibitor emavusertib results in lymphoma cell death in vitro with MYD88-mutated indolent B-cell lymphomas as a single agent and as a combination partner with BTK or PI3K inhibitors in unselected populations." (PMID 38068428, 2023). "This molecule still potently labeledRNF126 and also showed BTK degradation in MINO lymphoma cancer cells." (PMID 37252349, 2023). "Four BTK inhibitors have been used for the treatment of lymphomas: ibrutinib, acalabrutinib, zanubrutinib, and pirtobrutinib." (PMID 38068428, 2023). "The BTK inhibitor ibrutinib occupies an important position in lymphoma treatment because it brings a survival hope for patients with B-cell lymphoma, and promotes development of a chemotherapy-free era for such patients." (PMID 36588692, 2022). "Among them, ibrutinib is the first-in-class irreversible Bruton tyrosine kinase (BTK) inhibitor that induces apoptosis in lymphoma cells." (PMID 35406532, 2022). "Thirty-four of 58 LG-NHL patients had received anti-lymphoma treatment including rituximab, obinutuzumab alone or in combination with chemotherapy, or Bruton Tyrosine Kinase (BTK) inhibitors at the time of their vaccinations." (PMID 35875166, 2022). "Ibrutinib, a selective and irreversible BTK inhibitor, has been successfully utilized in various leukemia and lymphoma models." (PMID 33946867, 2021). "In this, the data available due to the single-drug approvals of BTK inhibitors such as ibrutinib or acalabrutinib for lymphomas in humans as well as the data on approved PI3K inhibitors will allow realizing this in a considerably shortened time frame." (PMID 34884478, 2021).
lymphoma (continued). "BTK is a kinase that regulates the immune responses of B- and T-cells, and blocking its activity can help suppress inflammatory responses and treat lymphomas and leukemias." (PMID 33492229, 2021). "Previous researches had showed high expression level of BTK phosphorylation in B cell lymphoma, which represented BTK activation and had correlation with lymphoma development." (PMID 33827598, 2021). "Inhibitors targeting BTK for treatment of these lymphomas have shown anti-tumor activity in lymphoma models, and three BTK specific inhibitors (Ibrutinib, Acalabrutinib, and Zanubrutinib) have FDA approval and are being used as a treatment option for patients." (PMID 34249912, 2021). "Its targeting by Ibrutinib, the first specific inhibitor, represented a turning point for the therapy of certain types of B-cell leukemias/lymphomas and several more BTK inhibitors are today in the clinic or advanced clinical trials." (PMID 34164404, 2021). "The combination of BTK and CSFR inhibition leads to mutually enhanced effects on co-cultures of MCL cells and lymphoma-associated macrophages." (PMID 32899476, 2020). "In our work, we primarily address aggressive Double-Hit lymphoma cells with a potentially less prominent dependence of the malignant B-cell towards sustained BTK signaling." (PMID 32824276, 2020). "We picked a novel BTK inhibitor, abivertinib, which is currently undergoing phase II clinical trials for lymphoma in our center." (PMID 32519423, 2020). "Bruton’s tyrosine kinase (BTK) is targeted in the treatment of B-cell disorders including leukemias and lymphomas." (PMID 33226337, 2020). "Supporting the notion that BTK is indispensable to B-cell and lymphoma survival, the targeting of BTK with the irreversible inhibitor ibrutinib has shown promising responses in R/R MCL." (PMID 32545704, 2020). "Next generation BTK inhibitors such as acalabrutinib and zanubrutinib are already used in other lymphomas." (PMID 32521744, 2020). "The new BTK-PROTAC induced rapid tumor regression of BTK-mutant-bearing lymphoma xenografts with limited signs of toxicity and showed even higher inhibitory activity when combined with Lyn, PI3K and Syk inhibitors." (PMID 32455989, 2020). "We became aware of the role of Bruton tyrosine kinase (BTK) in human innate immune responses from our studies of the BTK inhibitor ibrutinib in lymphoma, in which some patients developed invasive aspergillosis during treatment." (PMID 32503877, 2020). "In aggressive lymphomas, BTK inhibitors appear to be of particular benefit in lymphomas with activating mutations in MYD88 and CD79B." (PMID 33363034, 2020). "BTK has emerged as a novel molecular target in some B-cell leukemias and lymphomas where it is commonly overexpressed." (PMID 31200752, 2019). "BTK, a kinase critical for B-cell development, is a putative target in several cancers and BTK inhibitors have been shown to act synergistically with HDAC inhibitors in pre-clinical models of lymphoma." (PMID 29774113, 2018). "Bortezomib co-treatment with the BTK inhibitor ibrutinib in drug-resistant lymphoma also led to AKT inactivation." (PMID 27229530, 2016). "We first determined BTK expression in several lymphoma cell lines (Daudi Burkitt's Lymphoma line, and DB, Toledo, and RC-K8 Diffuse Large B-Cell Lymphoma (DLBCL) lines) and one T-cell leukemia line (Jurkat) by Western blot." (PMID 24759210, 2014).
lymphoma (continued). "Small molecule targeted drugs and CAR-T cell therapy, represented by BTK inhibitors and Bcl-2 inhibitors have achieved breakthrough results in the treatment of lymphoma, but they still face restrictions such as limited single-drug efficacy, drug-resistant recurrence, and toxic reactions." (PMID 41993181, 2026). "Given that most IP-LBCLs belong to the molecularly defined MCD subtype with shared biological features, BTK inhibitors may represent an optimal therapeutic backbone for this lymphoma entity." (PMID 40292282, 2025). "In lymphomas originating from B cells, the humoral immune response is severely impaired, and targeted therapies directed at B cells, such as CD20 antibodies, BTK inhibitors, and CAR-T cells, may cause B cell depletion and further suppress humoral immunity." (PMID 39140001, 2024). "Interestingly, the efficacy of BTK inhibitors in PCNSL is distinct from their performance in systemic lymphoma, where the single agent ibrutinib achieves only a 10% CR rate and a 15% PR rate." (PMID 39777345, 2024). "Research suggests that BTK inhibitors may regulate ferroptosis in lymphoma and other cancers, although further studies are needed to understand the role of BTK in ferroptosis fully." (PMID 39834804, 2024). "Because 1H MRS can be broadly used in cancer patients, our study indicates that such radiologic image-based monitoring should prove effective in lymphoma patients treated with a BTK inhibitor and, by extension, in patients with other malignancies treated with analogous kinase inhibitors." (PMID 38965536, 2024). "Given the established link between constant B cell receptor (BCR) activation, mediated by BTK, and CLL pathogenesis, the hypothesis regarding the detrimental impact of BTK inhibition on lymphoma cell survival gained traction." (PMID 39062757, 2024). "The impact of BTK inhibition on tumor metabolism reported here may have important translational implications for monitoring treatment response in patients with lymphoma and possibly other malignancies." (PMID 38965536, 2024). "BTK is known to enhance cyclin D2 expression that promotes the growth of lymphoma cells." (PMID 37705009, 2023). "Furthermore, IRAK-4 inhibition can synergize with drugs that inhibit BCR signaling pathways such as PI3K and BTK inhibitors to augment anti-lymphoma activity." (PMID 37954584, 2023). "SYK is of particular interest as a therapeutic target in leukemia and lymphoma as it plays a central role in activation of downstream kinases both via the BTK pathway and through its ability to directly phosphorylate and activate PI3K resulting in formation of second messenger PIP3 from PIP2." (PMID 36888611, 2023). "BTK inhibitors have transformed the therapeutic landscape for leukemias and lymphomas." (PMID 36903645, 2023). "Due to BTK’s significance in B-cell survival and proliferation, as well as its overexpression in various B-cell malignancies, it has been identified as a possible therapeutic target for the treatment of leukemias and lymphomas." (PMID 36903645, 2023). "Although BTK inhibitors like ibrutinib and acalabrutinib are viable treatment options for lymphoma patients, more pre-clinical studies focusing on BTK inhibition within the TME is necessary to completely understand how it contributes to solid tumor development." (PMID 34063667, 2021). "Along similar lines of research, a BTK/MNK (Mitogen-Activated Protein Kinase Interacting Kinase) dual inhibitor was developed for lymphoma and leukemia (QL-X-138), which interestingly establishes covalent binding to BTK and a standard reversible binding to MNK." (PMID 33401428, 2021). "BTK is mainly expressed in bone marrow–derived cells, and most studies have focused on BTK in terms of lymphoma, though others have suggested that BTK plays a vital role in the oncogenic process of solid tumors, such as colon cancer, ovarian cancer, and glioma." (PMID 34315851, 2021).
lymphoma (continued). "BTK inhibitors are currently approved by the FDA for the treatment of lymphoma and leukemia." (PMID 34880862, 2021). "BTKis inhibited BTK phosphorylation will inhibit lymphoma cells proliferation and increase overall survival in preclinical Burkitt lymphoma, and this effect could be enhanced by rituximab." (PMID 33827598, 2021). "Indeed, a successful example of such an approach is the development of the dual PI3Kδ/CK1ε inhibitor Umbralisib, which has shown clinical efficacy in relapsed/refractory CLL and lymphomas, alone, or in combination with BTK inhibitors." (PMID 34722279, 2021). "Additionally, a preclinical study identified the synergistic interaction of ricolinostat and ibrutinib the first-in-class BTK (Bruton’s tyrosin kinase) inhibitor in a large panel of lymphoma cell lines and in a xenograft model of lymphoma." (PMID 33024443, 2020). "More recently, BTK was successfully targeted by PROTAC-mediated degradation in ibrutinib-sensitive and resistant lymphoma cell lines, which may comprise a promising strategy for the treatment of BTK-resistant tumor cases." (PMID 30380749, 2018). "BTK target occupancy was evaluated in peripheral blood and lymphoma cells from FNAs." (PMID 27434128, 2016). "However, because roughly one third of MCL patients fail to respond to BTK inhibition upfront and essentially all responders eventually develop resistance to the drug, the methods to evaluate and monitor its effect on lymphoma cells are critical for optimizing personalized patient management." (PMID 39161974, 2024). "Furthermore, constitutive TLR signaling even in the face of BTK inhibition may explain the low response rates in some lymphomas." (PMID 37954584, 2023). "Consequently, targeting BTK has become a promising therapeutic approach in the treatment of various B‐cell lymphomas, offering the potential to disrupt these pro‐survival signals and inhibit lymphoma progression." (PMID 37929016, 2023). "Evidence demonstrating the expression of BTK on the majority of hematological cells has led to the hypothesis that BTK inhibitors (BTKIs) such as ibrutinib can be an effective treatment for leukemias and lymphomas." (PMID 36903645, 2023). "Besides genetic alterations, lymphoma B-cell growth is controlled by constitutively active protein kinases as demonstrated by the successful therapeutic strategy targeting Bruton’s Tyrosine Kinase (BTK) or Phosphoinositide 3 kinase (PI3K) in non-Hodgkin lymphomas." (PMID 36713383, 2022). "For example, the Bruton Tyrosine Kinase (BTK) protein, which is a tyrosine kinase and a crucial regulator of the BCR pathway, is excessively activated in various lymphoma cells." (PMID 41194439, 2025). "In summary, our data show that KAT/3BP exhibits significant in vitro and in vivo antitumor activity in lymphoma models, including those with primary resistance to R-CHOP and antibody–drug conjugates, as well as secondary resistance to BTK and PI3K inhibitors." (PMID 40563683, 2025). "A combination of the BTK inhibitor Zanubrutinib and the BCL2 inhibitor navitoclax synergistically induced apoptosis and ferroptosis to suppress growth in double-hit lymphoma." (PMID 40332068, 2025). "ISOIM/siBTK@Exosome displayed significant anti-lymphoma activity compared to ISOIM@Exosome or siBTK@Exosome alone, demonstrating synergistic therapeutic role of ISOIM and si-BTK." (PMID 41625362, 2025). "We next evaluated the correlation between CEACAM1 expression in lymphoma cells and their response to ibrutinib, which inhibits the BCR pathway kinase BTK." (PMID 40436855, 2025).
lymphoma (continued). "In our system, BM stromal cells (BMSCs) decreased lymphoma cell sensitivity to Phosphatidylinositol 3-kinase (PI3K) and BTK inhibitors." (PMID 41362022, 2025). "It has been reported to interact directly with Bruton's tyrosine kinase (BTK) and participate in the BCR signaling pathway—one of the critical survival pathways in lymphoma." (PMID 40993727, 2025). "RS represents a major unmet need in the lymphoma field, being refractory to standard and intensified chemoimmunotherapy approaches normally used for DLBCL and to novel CLL-targeted agents [Bruton tyrosine kinase (BTK) and BCL-2 inhibitors (BCL-2i)." (PMID 39728005, 2024). "By examining metabolic changes in response to ibrutinib treatment, particularly alterations in lactate, alanine, and choline concentrations, we can identify potential early and sensitive biomarkers of BTK inhibition in MCL and other lymphoma treatments." (PMID 39161974, 2024). "Subsequent efforts led to the development of BTK inhibitors such as PCI-32765, heralding a new era in lymphoma therapeutics." (PMID 39062757, 2024). "Subsequent approvals of a second generation of BTK inhibitors such as acalabrutinib (formerly ACP-196), orelabrutinib (ICP-022), and zanubrutinib (BGB-3111) for lymphoma treatment soon followed." (PMID 39062757, 2024). "Currently approved Bruton's tyrosine kinase (BTK) inhibitors have limited blood–brain barrier (BBB) permeability, which restricts their efficacy in treating central nervous system (CNS) lymphoma." (PMID 37929016, 2023). "Ibrutinib is a small-molecule covalent inhibitor of Bruton tyrosine kinase (BTK) and has been approved by the Food and Drug Administration (FDA) for the treatment of lymphoma, including chronic lymphocytic leukemia." (PMID 37741898, 2023). "In the Phase I/II TakeAim Lymphoma trial (NCT03328078), emavusertib is showing efficacy in several B-cell NHLs as a single agent and also in combination with the BTK inhibitor ibrutinib, even in patients with prior BTK inhibitor exposure." (PMID 37954584, 2023). "The IRAK4 inhibitor emavusertib was tested in two marginal zone lymphoma models (VL51 and Karpas1718) and their derivatives with secondary resistance to PI3K and BTK inhibitors." (PMID 36675328, 2023). "Overall, it was found that the expression of TrxR and BTK was positively correlated at both the mRNA and protein levels in DLBCL lymphoma cells, and that the inhibition of the expression of TrxR1 led to the downregulation of BTK expression." (PMID 36830087, 2023). "Ibrutinib is an oral inhibitor of Bruton tyrosine kinase (BTK) and has been approved by the FDA for the treatment of lymphoma." (PMID 37741898, 2023). "Combination therapy, including the combination of pembrolizumab or the Bruton’s tyrosine kinase (BTK) inhibitor, is also a preferred treatment option for aggressive lymphoma (described in detail below)." (PMID 36209106, 2022). "Thereafter, to inhibit BTK, we employ ibrutinib, a BTK inhibitor that is FDA approved for human therapeutic use in certain types of leukemia and lymphomas." (PMID 34895246, 2021). "Among them, Bruton’s tyrosine kinase (BTK) and phosphoinositide 3-kinase (PI3K) inhibitors have exhibited encouraging effects on human and canine leukemia and lymphoma." (PMID 34884478, 2021). "Irreversible inhibitors of Bruton tyrosine kinase (BTK), pioneered by ibrutinib, have become breakthrough drugs in the treatment of leukemias and lymphomas." (PMID 33526860, 2021). "One of the strategies to avoid acquired resistance and to increase the clearance of malignant lymphocytes is the combinations of PI3K inhibitors with other anti-lymphoma agents, including anti-CD20 antibodies, BTK inhibitors, or BCL2 inhibitors." (PMID 32197371, 2020). "Bruton’s tyrosine kinase (BTK) inhibitor has also been proposed as a combination therapy to HDAC inhibitor treatment, to overcome acquired resistance in lymphoma." (PMID 32575557, 2020).